HLA-DRB1 (major histocompatibility complex, class II, DR beta 1)
Diseases named in the same sentence as HLA-DRB1 in open-access papers (continued):
Sharing a sentence is not in itself a finding about the gene and the disease.
leprosy (continued). "Our gene-centric study identified genetic variants at TLR1 and HLA-DRB1/DQA1 as major determinants of leprosy susceptibility." (PMID 20617178, 2010). "In conclusion, this study suggests that TLR1 and HLA-DRB1/DQA1 are important genetic determinants of susceptibility to leprosy." (PMID 20617178, 2010). "Taken together, our association analysis of stratified patient groups indicates that the HLA-DRB1 locus is largely associated with leprosy per se, and only HLA-DRB1*09 shows an age-onset-dependent effect." (PMID 20003324, 2009). "In our study, more male cases were collected than female cases; thus, the observed association of the HLA-DRB1 allele with leprosy was based on a mostly male population." (PMID 20003324, 2009). "The polymerase chain reaction-sequence-specific oligonucleotide probe with Luminex100 (PCR-SSOP-Luminex) method was used to genotype HLA-DRB1 alleles in 305 leprosy patients and 527 healthy control individuals." (PMID 20003324, 2009). "The HLA-DRB1*15 allele was significantly more prevalent among leprosy patients than healthy controls, whereas the frequency of the HLA-DRB1*09 allele was lower among leprosy patients, especially those with early-onset disease." (PMID 20003324, 2009). "In the current study, we investigated the association of HLA-DRB1 with leprosy by genotyping DRB1 alleles in a large Chinese Han sample of 305 leprosy patients and 527 healthy control individuals." (PMID 20003324, 2009). "HLA-DRB1*15 has been demonstrated to be a leprosy-susceptibility allele among Brazilian and Indian populations." (PMID 20003324, 2009). "HLA-DRB1*08 was associated with a predisposition to LL leprosy (11.2% vs. 1.2%; P = 0.0037; OR = 12.00; CI = 1.51 – 95.12, pc = 0.0481), and HLA-DRB1*14 showed a tendency towards association with these patients (1.5% vs. 6.9%; P = 0.0595)." (PMID 19698125, 2009). "By analyzing a large number of Chinese leprosy patients, our study has provided the first evidence for an association of HLA-DRB1 with leprosy in a Chinese population and provided additional support for the important role of HLA in the pathogenesis of leprosy." (PMID 20003324, 2009). "We then investigated the association of HLA-DRB1* alleles with early-onset (age-at-onset ≤ 16 years; n = 141) and late-onset (age-at-onset > 16 years; n = 164) leprosy." (PMID 20003324, 2009). "Several studies reported an association of the HLA-DR2 alleles HLA-DRB1*15, *16 *04, *10 and *12 with susceptibility or resistance to leprosy in Brazilian, Vietnamese, South Indian, Indonesian, Thai and Argentine populations." (PMID 20003324, 2009). "Moreover, we replicated the previously associated HLA-DRB1*15:01 as leprosy risk factor and HLA-DRB1*04:05~HLA-DQA1*03:03 as protective alleles." (PMID 32776973, 2020). "Hence, HLA-DRB1*15:01 was indeed an independent leprosy risk factor for the Vietnamese patients which was also supported by the observation that HLA-DRB1*15:01 contributed significantly to leprosy risk independently of HLA-DRB1*10:01~ HLA-DQA1*01:05." (PMID 32776973, 2020). "The case-controlled analysis results showed a significant association between B leprosy and HLA-C*05 (5.94% vs. 14.02%; p = 0.002, OR = 0.38, 95% CI = 0.20–0.73, pc = 0.032) and HLA-DRB1*07 (16.34% vs. 26.77%; p = 0.003, OR = 0.53, 95% CI = 0.3–0.8, pc = 0.039)." (PMID 25605482, 2015). "To investigate whether the effect of HLA-DRB1* on leprosy risk was age-onset dependent, we stratified leprosy patients into early-onset (≤ 16 years) and late-onset (> 16 years) groups in association analyses." (PMID 20003324, 2009). "It has also been reported that certain HLA-DRB1 alleles are associated with MB or PB forms of leprosy, suggesting that HLA-DRB1 may also be involved in the clinical manifestation of the disease." (PMID 20003324, 2009).
leprosy (continued). "In addition, according to the data of the present study, HLA-DRB1*08 frequency was higher in lepromatous patients than tuberculoid patients, indicating a role in susceptibility to the most severe form of leprosy." (PMID 19698125, 2009). "In our study, we found that HLA-DRB1*15 was also associated with an increased risk of leprosy in a Chinese population, and exhibited an allele frequency (32%) similar to that observed in Indian populations (31%) but higher than that observed among Brazilians (15%)." (PMID 20003324, 2009). "This is consistent with the two-step model, suggesting that the HLA-DRB1 locus may influence the overall susceptibility to leprosy per se." (PMID 20003324, 2009). "We further investigated the association of HLA-DRB1* alleles with the clinical subtypes of leprosy." (PMID 20003324, 2009). "HLA-DRB1 alleles are associated with leprosy susceptibility in a Chinese population." (PMID 20003324, 2009). "The possibility of an association between class II HLA alleles and leprosy in a population from the south of Brazil was investigated in this study through the comparison of the HLA-DRB1, DQA1 and DQB1 allele frequencies of patients suffering the disease with those of a healthy control group." (PMID 19698125, 2009). "A study of the association of HLA-DRB1 alleles in 71 leprosy patients and 81 healthy controls in Argentina found a higher frequency of HLA-DRB1∗14:01 and HLA-DRB1∗14:06 alleles in leprosy patients compared to controls." (PMID 35664353, 2022). "Another study of genetic susceptibility to leprosy in India found rs1071630 located in HLA-DQA1 and rs9270650 in HLA-DRB1 associated with susceptibility to leprosy." (PMID 35664353, 2022). "We also described a molecular signature associated with neural damage in early stages of pure neural leprosy from patients (i.e., HLA-DRB1, MAPK14, GAP43, FABP7, NTN1, and LRRTM4)." (PMID 35492305, 2022). "The CNV esv3608598 is a deletion in the intergenic region of HLA-DRB1 and HLA-DQA1, both of which have been reported to be associated with leprosy risk in many countries." (PMID 34976012, 2021). "HLA-DRB1 is the most closely related gene to leprosy per se as well as clinical forms of the disease." (PMID 34976012, 2021). "Among the leprosy per se associated HLA alleles, HLA-DQA1*01:05 presented the most significant evidence of association (OR = 3.11, P = 7.61 × 10−10) followed by HLA-DRB1*10:01 (OR = 3.08, P = 1.02 × 10−9)." (PMID 32776973, 2020). "The results showed decreased frequencies of HLA-C*05 and HLA-DRB1*07 in B leprosy patients when compared to the healthy control individuals, suggesting that they are associated with protection against B leprosy." (PMID 25605482, 2015). "In leprosy patients from a Javanese population in Yogyakarta, Indonesia, HLA-DRB1*02 was associated with susceptibility to LL, while HLA-DRB1*12 was associated with resistance." (PMID 23936864, 2013). "In Chinese and Indian populations, HLA-DRB1/HLA-DQA1 locus, particularly HLA-DRB1*1501 was associated with leprosy." (PMID 22220182, 2011). "There were differences between leprosy per se patients and the control group for HLA-DRB1*16, which appeared with greater frequency in the patients (7.3% vs. 3.2%, P = 0.01, OR = 2.52, CI = 1.26–5.01, pc = 0.13)." (PMID 19698125, 2009). "It has been reported that leprosy-associated class II HLA genes include HLA-DRB1 in Vietnamese, HLA-DQA1/HLA-DPB1 in Brazilian, HLA-DQB1 in Mestizo, HLA-DRB1 in Argentinean, HLA-DRB1/HLA-DR-DQ in Chinese, and HLA-DQA1/HLA-DRB1 in Indian." (PMID 38440733, 2024). "In the association study between HLA-DRB1 and leprosy among Brazilian and Vietnamese people, the HLA-DRB1∗04 allele was associated with protection against leprosy, and the HLA-DRB1∗10 allele was found to be associated with susceptibility to leprosy." (PMID 35664353, 2022).
leprosy (continued). "In addition, haplotypes containing HLA-DRB3~ HLA-DRB1*12:02 and HLA-C*07:06~ HLA-B*44:03~ HLA-DRB1*07:01 alleles were found as two independent protective factors for leprosy." (PMID 32776973, 2020). "To test for leprosy associations independent of HLA-DRB1*10:01~ HLA-DQA1*01:05, we conducted a forward conditional association analysis of the 20 significantly associated alleles until markers presented Pconditional ≥ 0.01." (PMID 32776973, 2020). "However, we noted that the HLA-DRB1*01 group was more frequent in leprosy cases than in healthy controls (frequency of 0.7% and 0.3% respectively)." (PMID 32776973, 2020). "In addition to HLA-DRB1, variants in HLA-DQA1 and HLA-C were also associated with leprosy in the Chinese population." (PMID 32776973, 2020). "Previously, two small studies reported a leprosy per se risk effect of HLA-DRB1*15:01 and a serotype linked to HLA-DQA1*01, and a well powered study of Brazilian leprosy patients detected a risk effect for both HLA-DRB1*10 and HLA-DRB1*15." (PMID 32776973, 2020). "Furthermore, we demonstrate for the first time that HLA-DRB1*09 has an impact on the onset of disease, exerting a protective effect only against early-onset leprosy." (PMID 20003324, 2009). "The association of HLA-DRB1 with leprosy has been reported in several populations, but not in a Chinese population." (PMID 20003324, 2009). "In the present study, HLA-DRB1*16, a subtype of DR2, participates as a susceptibility marker for leprosy per se, confirming previous serological results that showed an association between HLA-DR2 and leprosy per se in patients from an equivalent geographical area (South Brazil)." (PMID 19698125, 2009). "There was a positive association of HLA-DRB1*16 (*1601 and *1602) with leprosy per se (7.3% vs. 3.2%, P = 0.01, OR = 2.52, CI = 1.26–5.01), in accord with previous serological studies, which showed DR2 as a marker of leprosy." (PMID 19698125, 2009). "However, HLA-DRB1*15:01 was found to be significantly associated with MAC infection and leprosy." (PMID 28437431, 2017). "For HLA class II (HLA-DR and DQ), the most consistent findings are that HLA-DR2 (subtypes HLA-DRB1*15 and HLA-DRB1*16) and HLA-DQ1 (subtypes HLA-DQB1*05 and HLA-DQB1*06) are associated with the TT and LL clinical forms, respectively, and are also associated with leprosy per se." (PMID 25605482, 2015). "Further studies will be needed to investigate the association of the LTA+80 locus with leprosy in Chinese populations and determine whether the association at the HLA-DRB1 locus is independent of the LTA+80 locus." (PMID 20003324, 2009). "Interestingly, we found that HLA-DRB1*09 was associated with protection effect against early-onset leprosy (P = 0.003), but not late-onset leprosy (P = 0.285)." (PMID 20003324, 2009). "In both the Vietnamese and the Chinese populations, HLA-DQB1*04:01 is part of a haplotype which includes HLA-DQA1*03:03 and HLA-DRB1*04:05, and in a meta-analysis of studies in Chinese patients HLA-DQA1*03:03 was identified as main leprosy resistance factor." (PMID 32776973, 2020). "This case-control study investigated the genetic variation present in HLA-DRB1, DQA1 and DQB1 genes, and its relation to leprosy in Southern Brazil." (PMID 19698125, 2009). "The association between disease and HLA-DR-DQ loci surveyed in this study is not different from the relationship between leprosy and HLA-DRB1 identified in previous studies." (PMID 35769990, 2022).
systemic sclerosis (20 papers, 2012 to 2025). A chronic disorder, possibly autoimmune, marked by excessive production of collagen which results in hardening and thickening of body tissues. "HLA-DRB1*07:01 has been found to be associated with protection in systemic sclerosis in European origin individuals." (PMID 34163474, 2021). "HLA-DRB1*11 expression has been associated to the rate of systemic sclerosis and promotes the induction of anti-DNA topoisomerase I Abs." (PMID 32854442, 2020). "al. summarized a comprehensive correlation of the most significant associations within HLA-DRB1*04:04 and HLA-B*37, emphasizing that the alleles associated with morphea were different from those associated with systemic sclerosis (SSc), indicating that morphea is immunogenetically distinct from SSc." (PMID 39685593, 2024). "Increased prevalence of systemic sclerosis in African-Americans might be partially due to a higher frequency of HLA-DRB1*08:04 and HLA-DRB1*11:02 alleles, which are also associated with higher risk for SSc development." (PMID 37239884, 2023). "There are minor criteria in which specific HLA (HLA DQB1 and HLADRB1) are highlighted and AIDs such as multiple sclerosis (MS) and systemic sclerosis (SSc) are involved." (PMID 23119159, 2012). "Specifically, HLA-DRB1*1101 was more prevalent among White and African American individuals with anti-topo I autoantibodies, whereas a higher frequency of DRB1*1104 was observed in Hispanics compared to anti-topo I-negative systemic sclerosis (SSc) patients." (PMID 38790215, 2024).
psoriasis (19 papers, 2008 to 2026). An autoimmune condition characterized by red, well-delineated plaques with silvery scales that are usually on the extensor surfaces and scalp. "Genotype integration reveals that HLA-DQA1*01 and HLA-DRB1*15 genotypes are positively associated with baseline psoriasis severity." (PMID 41565778, 2026). "In contrast, HLA-Cw*0702 and HLA-DRB1*08 allele frequencies were increased compared with psoriasis patients and normal population in Taiwan." (PMID 30650098, 2019). "In contrast, HLA-Cw*0702 and HLA-DRB1*08 allele frequencies were increased compared with normal population and psoriasis patients in Taiwan." (PMID 30650098, 2019). "Since then, the polymorphism of HLA-DRB1 and its relationship with the psoriasis, as well as the role of HLA-DRB1 alleles in the pathogensis of psoriasis have been reported in different works." (PMID 27713139, 2017). "In contrast to the other healthy subjects, CON09 (a patient with psoriasis) expressed the long transcript variant of HLA-DRB1 and a high level of HLA-DRB5 protein, similar to patients in the NM group." (PMID 28052121, 2017). "HLA-Cw*06 and HLA-DRB1*07 are associated with patients with PsA having type I psoriasis, suggesting that the primary association is with age of onset of psoriasis." (PMID 17728335, 2008). "HLA-DRB1*07, in linkage disequilibrium with HLA-Cw*06, was also associated with patients with PsA having type I psoriasis (OR 2.7, 95% CI 2.1, 3.7, p<0.00001)." (PMID 17728335, 2008). "Stratification analysis showed that the HLA-DRB1*07 phenotype was strongly associated in those patients with PsA with type I psoriasis (OR 2.7, 95% CI 2.1, 3.7 and p<0.00001) compared with controls." (PMID 17728335, 2008). "Furthermore, the rs660895 SNP within the HLA-DRB1 gene has shown an association with an increased risk of psoriasis, particularly in early-onset cases." (PMID 37569685, 2023). "An increase in T cell immunoreactivity against specific myelin antigens and the development of lesions in the brainstem and cerebellum was found in patients with MS and psoriasis who demonstrated a high frequency of carriage of the HLA-DRB1*1501 and HLA-DRB1*07 alleles." (PMID 35854235, 2022). "It is known that patients with psoriasis express certain HLA-DRB1 alleles." (PMID 28052121, 2017). "In contrast, specific Class II alleles, particularly HLA-DRB1*07:01 g, HLA-DQB1*02:01g, and HLA-DQB1*03:01g, showed higher loading distances, suggesting a stronger influence in distinguishing psoriasis cases from controls." (PMID 41512531, 2026). "On loading plot, specific Class II alleles, particularly HLA-DRB1*07:01 g, HLA-DQB1*02:01g, and HLA-DQB1*03:01g, showed higher loading distances, suggesting a stronger influence in distinguishing psoriasis cases from controls." (PMID 41512531, 2026). "HLA-DRB1*08 was found to be associated with psoriatic polyarthritis, and it was the second most common allele in our study, with higher frequency compared with psoriasis patient and normal population in Taiwan, which may indicate it is a risk factor for psoriatic polyarthritis." (PMID 30650098, 2019). "In PsA patients, increased frequency of HLA-DRB1*0701 compared with controls had been reported, but its frequency was lower than uncomplicated psoriasis patients." (PMID 30650098, 2019). "To investigate the specific role of hypomethylation of HLA-DRB1 in the pathogenesis of psoriasis, in the following step, we plan to perform animal studies using the existing psoratic models." (PMID 27713139, 2017). "A number of SNPs in HLA-DRB1 have been found being associated with the risk of psoriasis, however it is unclear that metylation status within HLA-DRB1 in psoriasis." (PMID 27713139, 2017). "In this study, we will focus on the methylation status of HLA-DRB1 in psoriasis and its relationship with the disease." (PMID 27713139, 2017).